CRP (C-reactive protein)
Diseases named in the same sentence as CRP in open-access papers (continued):
Sharing a sentence is not in itself a finding about the gene and the disease.
infection (5,152 papers, 1998 to 2026). The state of being infected such as from the introduction of a foreign agent such as serum, vaccine, antigenic substance or organism. "Suboptimal vitamin D status was present in 64.3% of patients and was associated with higher median CRP levels (3.84 vs. 1.42 mg/dL, p = 0.025) and a greater prevalence of Salmonella infection (48.9% vs. 24.0%, p = 0.047)." (PMID 41829997, 2026). "Taken together, these findings suggest that Hs-CRP is closely associated with infection severity, amputation risk, and adverse short-term outcomes in DFU patients, and appears to outperform procalcitonin in diagnostic accuracy." (PMID 41601759, 2026). "Dynamic inflammatory marker patterns correlated with infection timing, and early peaks of CRP, WBC, and IL-6 were associated with worse outcomes." (PMID 41597404, 2026). "As the optimal set of predictors for postoperative infection risk assessment still has to be investigated, we cannot conclude yet on the superiority of either IL-6 or CRP when used in combination with such a set of predictors for postoperative infection." (PMID 40549692, 2025). "This means that when CRP is low or trending downward by the fourth day, the likelihood of a significant infection is low, whereas persistently high CRP at that point is cause for concern." (PMID 41153812, 2025). "Basically, CRP is synthesized by IL-6 in the liver, and these molecules are produced in large quantities when the body becomes susceptible to infection; because of this reason, they are easily found in serum." (PMID 40095921, 2025). "This adds a level of complexity; therefore, biomarkers more associated with infection than inflammation had a discriminative advantage over the inflammatory markers, e.g., IL-6, IL-8, CRP, PCT, lactate, TREM-1, and uPAR." (PMID 39857101, 2025). "Maximum IL-6 concentrations were associated with postoperative infection (adjusted odds ratio (aOR) 1.04 per 10 pg/ml, 95% confidence interval (CI) 1.00–1.09, p = 0.047) as was CRP (aOR 1.01 per mg/L, 1.00–1.03, p = 0.032)." (PMID 40549692, 2025). "CRP, an acute-phase protein produced by the liver in response to inflammation, has been widely studied as a diagnostic tool for detecting post-surgical infections." (PMID 40342430, 2025). "IL-6 is a cytokine involved in inflammatory reactions, and the IL-6 inhibitory effect of satralizumab suppresses fever symptoms and increase in blood level of C-reactive protein, which poses a risk of delaying the detection of infection." (PMID 39470886, 2025). "Indicators reflecting infection showed that higher values tended to be associated with good renal recovery, while the significant infection marker CRP yielded ambiguous results." (PMID 40101226, 2025). "Diagnostic testing for infection include laboratory results (CRP, white blood cell count, leucocyte count), radiological imaging methods (conventional imaging, CT-scan, MRI-scan, 3-phase bone scan, FDG-PET) and microbiological deep tissue sampling." (PMID 40156733, 2025). "Preoperative biomarker trends were also explored, with some studies identifying CRP, albumin, and eGFR as potential predictors of surgical site infection risk in elective procedures." (PMID 40342430, 2025). "Several laboratory parameters—particularly lymphocyte count and C-reactive protein (CRP)—showed counterintuitive associations with infection status, illustrating the complexity of interpreting inflammatory biomarkers in medically managed settings." (PMID 40869330, 2025). "Positive Ga-68 citrate scan findings for infection had a statistically significant association with inflammatory markers CRP (p = 0.001), which was high in 75% (n = 25/33) patients." (PMID 41502998, 2025). "Trials often use CRP as a surrogate marker of inflammation, but elevated CRP also is associated with a higher risk of future infection-related death events." (PMID 40796058, 2025).
infection (continued). "Fever represents a physiological stress response to infection or inflammation, often associated with elevated CRP levels and a concomitant reduction in HDL-C levels." (PMID 40607030, 2025). "Maximum CRP concentrations were also associated with postoperative infection (aOR 1.01, (95% CI 1.00,1.03)) and significantly improved model fit (LRT p = 0.032)." (PMID 40549692, 2025). "Even a short preoperative course with synbiotics reduced IL-6 and CRP levels and also reduced the risk of infection by 85%." (PMID 40671981, 2025). "Permanent AF was associated with elevated CRP levels, but this elevation was unrelated to early infection with Chlamydia pneumoniae and H. pylori." (PMID 40351687, 2025). "For both lipidomics and metabolomics, C‐reactive protein (CRP) was significantly associated with infection." (PMID 40411399, 2025). "Maximum IL-6 and CRP concentrations within 24 hours from the start of surgery were associated with postoperative infection." (PMID 40549692, 2025). "This biomarker, which reflects circulating iron stores, is affected by infection and inflammation, necessitating the inclusion of additional markers such as C-reactive protein, to appropriately classify individuals as iron deficient or sufficient." (PMID 41037236, 2025). "Studies have shown that CRP is significantly associated with postoperative infections and complications." (PMID 41019129, 2025). "The results indicate that age, duration of surgery, blood transfusion, internal fixation, postoperative NLR and postoperative CRP/ALB are risk factors for the development of infection after spinal surgery." (PMID 41019129, 2025). "Incorporating specific changes and thresholds of BT, WBC, and CRP post-TAVR into the RIAT score improved risk prediction for infection, underscoring its utility in enhancing antibiotic stewardship in this growing patient population." (PMID 39918726, 2025). "The aim of this study was to evaluate the diagnostic value of postoperative serum C-reactive protein (CRP) concentrations for identifying early surgical site infections (SSI) in patients undergoing scoliosis correction surgery." (PMID 41226908, 2025). "On univariate analysis, higher mean arterial pressure, PF ratio, and CRP levels were associated with a lower mortality, as were the presence of infection with S. pneumoniae, and lobar consolidation on chest radiograph." (PMID 40665761, 2025). "In the four-parameter model, MDW (OR: 1.67 per unit increase; P < 0.0001) and CRP (OR: 1.17 per 1 mg/dL increase; P = 0.0006) were independently associated with infection, yielding an AUC of 0.890 (95% CI, 0.827–0.952)." (PMID 40460177, 2025). "Patients with persistently elevated CRP values experienced delayed wound closure, higher rates of secondary infection, and greater amputation risk." (PMID 41367458, 2025). "Although CRP is commonly associated with infection, it has been suggested that it is associated with various types of cancer, such as breast, colorectal, and lung cancer." (PMID 40141426, 2025). "With only six microbiologically confirmed cases and 70% solid-tumor patients, the study underscores CRP’s inconsistent diagnostic utility in febrile neutropenia, particularly for infection confirmation." (PMID 40647525, 2025). "Decreased platelet counts at infection onset and elevated CRP levels were also associated with higher mortality." (PMID 40724002, 2025). "Elevated preoperative or early postoperative NLR was consistently associated with significantly increased odds of infection, with a pooled OR of 2.54, while CRP/CAR also showed strong predictive performance with a pooled OR of 2.43." (PMID 41018345, 2025). "If CRP is to be used as a biomarker for CMTs, it is crucial to exclude any underlying infection conditions." (PMID 40095734, 2025). "Some of the risk factors, such as peripheral pulsation and infection markers (CRP and ESR), are clinical and lab-based assessments, which can vary between practitioners and institutions." (PMID 39935923, 2025).
infection (continued). "By combining CRP and fibrinogen levels, clinicians can simultaneously assess the widespread inflammation and the local clotting activity associated with infection." (PMID 41250763, 2025). "Temperature, ANC, and CRP are obtained as part of the initial evaluation in virtually all pediatric FN episodes in our setting and allow a rapid, objective appraisal of infection risk." (PMID 41462806, 2025). "Plasma IL-6 and CRP levels observed within 24 hours from the start of surgery are associated with postoperative infection risk, yet the added value of these biomarkers to a simple clinical prediction model seems limited." (PMID 40549692, 2025). "CRP, an acute‐phase reactant associated with inflammation and infection, is widely used as a clinical biomarker for inflammation." (PMID 40329709, 2025). "CRP values ​​were significantly higher in patients with possible additional causes of inflammation, such as infection." (PMID 39521708, 2025). "This study identified the previous antibiotic therapy, surgical therapy, ulcer size>4cm2 and CRP level as independent risk factors for MDRO infections." (PMID 41458536, 2025). "Similar to our findings, in a recent study ICIS demonstrated a diagnostic performance for early infection detection at admission, with an AUC of 0.958, outperforming CRP, PCT and IL6." (PMID 40471473, 2025). "The findings indicate that CRP remains a widely used and effective biomarker for early infection detection, with its diagnostic accuracy varying depending on the type of surgery and the POD on which it is measured." (PMID 40342430, 2025). "High IL-6 levels promote the production of CRP in the liver, which is linked to infection, trauma, and cardiovascular and renal complications." (PMID 40572756, 2025). "Elevated CRP has been associated with infection, poor metabolic control, and higher rates of adverse outcomes in DFU patients, including delayed healing and amputation." (PMID 41367458, 2025). "In the early stages of severe infections, the immune system can be over-activated, producing large amounts of inflammation-associated factors such as CRP, calcitoninogen and IL-6." (PMID 40373091, 2025). "Second, immune biomarkers such as SAA and CRP are susceptible to confounding factors like infection or medication, potentially introducing variability; future studies should consider dynamic monitoring to improve precision." (PMID 41255770, 2025). "Elevated CRP levels are commonly associated with postoperative complications, including infection and tissue damage." (PMID 40142907, 2025). "The vancomycin plus amikacin regimen (Group C) was associated with lower rates of ESR, CRP, colonization, and clinical infection, potentially due to its broader Gram-positive coverage, including MRSA, compared to cefazolin." (PMID 40841631, 2025). "They further found that higher IPF levels were associated with infection severity, and that their combination with CRP or PCT enhanced early diagnostic performance." (PMID 40723124, 2025). "We observed strong positive correlations with underlying conditions (r = 0.55), ICU admission (r = 0.80), infection duration (r = 0.78), remdesivir treatment (r = 0.81), leukocyte count (r = 0.66), and CRP (r = 0.78)." (PMID 40592354, 2025). "All 135 patients were tested for infection-related indicators such as routine blood, CRP, and PCT on the day of pathogenic microbiological examination." (PMID 41574363, 2025). "Patients with the highest CRP values were evaluated to assess infections as a cause of high CRP and driver of mortality." (PMID 40208300, 2025). "In this retrospective study, our goal is to assess the diagnostic value of PCT, WBC, and CRP elevations in detecting bacterial infections and differentiating between infection and SIRS in the early postoperative period after LT." (PMID 41007066, 2025). "In a standard blood draw, elevated levels such as C-reactive protein (CRP), albumin or hemoglobin can be used to assess the risk of infection." (PMID 39210389, 2024).
infection (continued). "In contrast, fever and increased CRP level lasting > 7 days after decannulation were related to active infection, which was significantly associated with in-hospital mortality." (PMID 39797141, 2024). "The logistic analyses result showed that fever time upon admission (hour), peak fever, WBC, neutrophils percentage, CRP and convulsion frequency were independent risk factors for hospitalization of children with Omicron Variant infection." (PMID 38464898, 2024). "We also investigated the causal association between the levels of CRP, a marker of systemic inflammation, and IgAN levels, as circulating immune cell abundance is particularly susceptible to changes associated with infection or injury." (PMID 39221249, 2024). "Given the risk of infection following cervical cerclage, her temperature, white blood cell count, and CRP levels were closely monitored within the first 48 h after surgery, with results indicating no signs of infection." (PMID 39659804, 2024). "In clinic routine, CRP is frequently measured as a diagnostic tool for infection, as a marker for disease severity, as well as for the assessment of the therapeutic response (i.e., following antibiotic therapy)." (PMID 37204560, 2024). "As a result, the use of biomarkers of inflammation or infection, such as procalcitonin and C-reactive protein (CRP), as a guidance in the diagnostic process has been recommended." (PMID 39727640, 2024). "The results showed that fever time upon admission (hour), peak fever, WBC, neutrophils percentage, CRP and convulsion frequency were independent risk factors for hospitalization of children with Omicron Variant infection (P < 0.05)." (PMID 38464898, 2024). "Increased antibody level was also found to be associated with the timing of active infection as evidenced by increased C-reactive protein (CRP) and white blood cell (WBC) count levels." (PMID 37947190, 2024). "Leucocyte counts, C-reactive protein, pregnancy week, eGFR, and hemoglobin appeared as significant predictors of high risk of severe infection requiring ICU admission." (PMID 39768627, 2024). "Both infection and stress are associated with an increased presence of inflammatory biomarkers, including tumor necrosis factor alpha and C-reactive protein." (PMID 39536047, 2024). "In previous research, infection was identified as the most frequent cause of elevated CRP levels (55.1%), followed by rheumatologic diseases, other inflammatory conditions, and malignancy." (PMID 39594253, 2024). "Generally, the high levels of CRP and fibrinogen indicated a more intense infection associated with prolonged hospitalization." (PMID 39064086, 2024). "Elevated levels of the erythrocyte sedimentation rate, hemoglobin, and CRP have been indicative of an increased risk of infection." (PMID 39063921, 2024). "CRP is an indicator of a general acute reaction in inflammation, infection and tissue injury that is associated with cognitive dysfunction." (PMID 39189543, 2024). "In adults, prospective studies have shown that higher CRP levels are associated with increased susceptibility to infection." (PMID 39479595, 2024). "Subsequently, we assessed the diagnostic capabilities of CRS, fever, PCT, IL-6, and CRP in the early diagnosis of infection in febrile patients after CTI using the ROC curve and the Youden’s index." (PMID 38956649, 2024). "After evaluating the associations between suPAR, infection status, and CRP, we expanded our analysis to encompass a broader range of inflammatory biomarkers and their potential change in response following brain injury." (PMID 39540961, 2024). "For decades, interleukin 6 (IL‐6), procalcitonin (PCT), and C‐reactive protein (CRP) have been widely investigated to identify pathogenic bacteria, evaluate the severity of infection, and predict adverse outcomes in cancer patients." (PMID 38967137, 2024).
infection (continued). "The serum erythrocyte sedimentation rate (ESR) and C-reactive protein (CRP) are two laboratory diagnostic tests that help provide valuable information regarding inflammation and infection." (PMID 39204094, 2024). "Early studies indicated that elevated preoperative CRP levels significantly increased the risk of infection, cardiovascular, and cerebrovascular complications." (PMID 39536046, 2024). "From our study’s perspective, since the initiation of anti-TB treatment caused a significant decline in serum CRP levels, it appears that drug exposure at the site of infection was sufficient for effective early Mtb killing." (PMID 39766606, 2024). "Elevated CRP levels are associated with infections, trauma, surgery, and chronic inflammatory conditions." (PMID 39595661, 2024). "There are, however, reports of CRP variants associated with the clinical outcomes of other infections and the response to vaccination." (PMID 38662664, 2024). "C-reactive protein (CRP) is a pivotal biomarker in the acute phase response of the innate immune system, commonly associated with inflammation, infection, and tissue injury." (PMID 39337259, 2024). "Elevated ESR and CRP levels were more common in patients with advanced age or a history of cancer, indicating a higher risk of infection or inflammatory conditions." (PMID 39594253, 2024). "A higher EPA/AA ratio prior to infection was found to be associated with lower concentration of C-Reactive Protein and interleukin-6, leading to a better prognosis of hospitalized SARS-CoV-2 patients." (PMID 38702342, 2024). "Further, CRP levels can be volatile and their elevation is multifactorial in the course of the disease, in particular as infection associated with rises in CRP levels is one of the most prevalent reasons for unplanned ED visits of cancer patients." (PMID 39414641, 2024). "Infections susceptible to baseline antimicrobials were associated with higher CRP responses than resistant infections, possibly due to increased initial inflammatory responses from antimicrobial killing or reduced fitness costs from antimicrobial resistance." (PMID 38599549, 2024). "A systematic review suggested that while CRP cannot independently diagnose infection, it serves as an indicator necessitating follow-up and analysis of pre- and post-surgery CRP levels to understand underlying causes." (PMID 39536046, 2024). "Infection and tissue injury, such as acute myocardialinfarction, surgical trauma, tumours and other factors, can also cause CRP levelsto increase." (PMID 39742221, 2024). "The persistence of high serum CRP levels can be explained by factors other than the persistence of active infection and was associated with unfavorable clinical evolution in other studies." (PMID 39272020, 2024). "In one case, the infection was caused by Staphylococcus aureus, where the pH was 7.71, and this correlated with a low CRP of 19.8 mg/L." (PMID 38337382, 2024). "Postoperative increases in CRP and leucocyte counts were associated with clinical signs of infection in individual cases." (PMID 39064142, 2024). "For example, CRP levels greater than 10 μg/mL are indicative of clinically evident inflammation, primarily caused by infection." (PMID 39337259, 2024). "In response to infection and injury, IL-6 mediates acute-phase reactants such as C-reactive protein (CRP) and is associated with clinical sequelae such as fever, fatigue, bone loss and stress hormone production." (PMID 38928238, 2024). "Acute pain, especially when caused by an inflammatory process, trauma, or infection, can lead to elevated CRP levels in the blood." (PMID 38384869, 2024). "Elevated levels of Infection-associated tests include SAA, PCT, CRP, and IL-6 indicate the presence of infection." (PMID 39267743, 2024).